MMP9 (matrix metallopeptidase 9)
Diseases named in the same sentence as MMP9 in open-access papers (continued):
Sharing a sentence is not in itself a finding about the gene and the disease.
injury (continued). "Therefore, targeting MMP9 might provide a practical clinical strategy for the patients with brain injury." (PMID 33224434, 2020). "However, accumulating evidences revealed that MMP-9 (matrix metalloproteinase 9) played a crucial role in modulating the permeability of BBB under various pathological conditions such as head trauma, acute liver failure, focal or global ischemia and reperfusion." (PMID 23469092, 2013). "In a mouse model of traumatic brain injury, CORM-3 was shown to reduce pericyte death and MMP-9 expression at pericyte somata." (PMID 29929562, 2018). "Here, using a selective JNK inhibitor, SP600125, and the downstream MEK inhibitor of ERK, PD98059, we focused on the roles of JNK and ERK in LPS-induced acute lung injury and production of CINC, MMP-9, and NO." (PMID 15566575, 2004). "In a model of acute lung injury, genistein has been shown to suppress cytokine-inducible neutrophil chemoattractant (CINC) and matrix metalloproteinase-9 (MMP-9) production leading to the inhibition of neutrophil infiltration and activation, and the reduction of MPO activity." (PMID 35927726, 2022). "In addition, HDAC4 inhibition has been shown to prevent increases in MMP-9 and hence EMT in a mouse model of bleomycin-induced acute lung injury." (PMID 30068332, 2018). "In addition, inhibiting HDAC4 suppressed MMP-9 elevation and hence EMT in a mouse model of bleomycin-induced acute lung injury." (PMID 30068332, 2018). "Our previous study showed that intrathecal injections of MMP-9 siRNA specifically reduced MMP-9 but not MMP-2 activity in DRGs after nerve injury." (PMID 22444868, 2012). "In bleomycin-induced pulmonary injury mice model, AUDA significantly attenuated inflammation by inhibiting p38-MAPK signaling pathways, and therefore reduced inflammatory cell accumulation and decreased the expression of interleukin-1β, TGF-β, and matrix metalloproteinase 9 (MMP-9)." (PMID 35744996, 2022). "Therefore, no obvious interaction exists between MMP-9 and IL-1β following disruption of BBB secondary to brain trauma/stress." (PMID 27795859, 2016).
nasopharyngeal carcinoma (40 papers, 2009 to 2025). A carcinoma arising from the nasopharyngeal epithelium. "A meta-analysis showed that MMP-9 overexpression is significantly associated with poor overall survival (HR: 1.65) and shortened disease-free survival (HR: 1.61) in nasopharyngeal carcinoma." (PMID 33817161, 2019). "The effect of N-cadherin on matrix metalloproteinase 9 (MMP-9) regulation is implicated in human nasopharyngeal carcinoma (NPC) cell invasion." (PMID 27737648, 2016). "Subsequent studies that investigated the prognostic role of MMP9 rs2250889 in 200 nasopharyngeal carcinoma patients showed increased death risk (HR = 2.287, 95% CI = 1.400–3.735) in subjects with MMP9 rs2250889 encoded p.574Pro/Pro and p.574Pro/Arg genotypes compared to p.574Arg/Arg genotype." (PMID 29138529, 2017). "The findings from our and others’ studies implicate the use of EF-24 as a promising modality to restrain the anti-metastatic potential of nasopharyngeal cancers by targeting MMP-9." (PMID 36900342, 2023). "In nasopharyngeal carcinoma, senescent cells promote tumor cell invasion by increasing the secretion of matrix metalloproteinase 9 (MMP 9)." (PMID 37303739, 2023). "For example, VEGF enhances the expression of EMT markers N-cadherin, vimentin, and MMP2 and MMP9, reduces the expression of E-cadherin, promoting the invasion and migration of nasopharyngeal carcinoma cells." (PMID 35371324, 2022). "Liu and colleagues synthetized a copolymer with β-cyclodextrin (CD) core and poly(l-lysine) dendron (PLLD) to co-deliver docetaxel antitumor drug and MMP-9 siRNA plasmid for nasopharyngeal carcinoma therapy." (PMID 30413047, 2018). "MMP-9 siRNA was more effective for nasopharyngeal carcinoma therapy, when a folate modified (FA-CD-PLLD) was employed as targeting moiety." (PMID 30413047, 2018). "For the targeting co-delivery of hydrophobic drug and gene effectively, a FA modified star-shaped copolymer (FA-CD-PLLD) has been synthesized and used to targeting co-deliver DOC and MMP-9 for nasopharyngeal cancer therapy." (PMID 27259274, 2016). "Epstein Barr is strongly related to the promotion of nasopharyngeal cancer and also with the expression of MMP-9." (PMID 20386655, 2010). "As2O3 reduced the expression of MMP-9 by nasopharyngeal carcinoma cells in vitro, and decreased their invasive and metastatic properties." (PMID 19804631, 2009). "Additionally, in vitro-induced CS studies have shown that enhancing the secretion of MMP-9 can promote nasopharyngeal carcinoma progression of nasopharyngeal carcinoma." (PMID 41197720, 2025). "In a similar way, millimolar melatonin reduced the migration and metastatic invasion of nasopharyngeal carcinoma cells through the suppression of MMP-9 expression by inhibiting the binding of the transcription factor, specificity protein-1 (SP-1) to DNA at the MMP-9 promoter." (PMID 31684096, 2019). "Similarly, the Casp12 degraded IκBα protein and enhanced MMP-9 expression in human nasopharyngeal carcinoma (hNC) cell invasion." (PMID 31557882, 2019). "Exposure of human nasopharyngeal carcinoma (NPC) cells to phorbol-12-myristate-13-acetate (PMA) increased the levels of Casp12 and MMP-9 resulting in NPC cell invasion." (PMID 28380444, 2017). "The aim of the present study was to analyze the expression of matrix metalloproteinase 9 (MMP9) in nasopharyngeal carcinoma (NPC) and its correlation with clinicopathologic features, including the survival of patients with NPC." (PMID 20534121, 2010). "Using real-time PCR, we detected the mRNA expression of MMP9 in normal nasopharyngeal tissues and nasopharyngeal carcinoma (NPC) tissues." (PMID 20534121, 2010). "It has been shown that NQO1 expression is enhanced, while MMP9 and PCNA expression is downregulated with the declining deuterium concentration in nasopharyngeal carcinoma cells (NPCs)." (PMID 38732643, 2024).
nasopharyngeal carcinoma (continued). "MMP14 not only promotes cell migration, invasion, and angiogenesis in nasopharyngeal carcinoma and pituitary adenomas but also promotes the secretion of pro-MMP2 and pro-MMP9." (PMID 30886783, 2019). "Moreover, in nasopharyngeal carcinoma, FSTL1 blocks Wnt7a inhibition of ERK phosphorylation, inducing MMP9 production, extracellular matrix degradation, and metastasis." (PMID 38605354, 2024). "In addition, target genes, such as MMP-9, vimentin (VIM), and CDH1, which were found to be differently expressed in the nasopharyngeal carcinoma cells transfected with miR-10b mimics and with miR-10b inhibitors, were also involved in migration and invasion." (PMID 29262659, 2017). "In vivo assays showed that FA-CD-PLLD/DOC/MMP-9 could inhibit HNE-1 tumor growth and decrease PCNA expression effectively, indicating a promising strategy for nasopharyngeal carcinoma therapy." (PMID 27259274, 2016). "In nasopharyngeal carcinoma, DEPDC1 knockdown downregulated various downstream targets, such as c−Myc, BCL2, MMP2 and MMP9, which participated in proliferation, tumorigenesis, and metastasis, suggesting that DEPDC1 might be a vital factor in these biological processes." (PMID 36768316, 2023). "Nasopharyngeal carcinoma cells treated with PDT showed that IL-8, IL-1α, IL-1β, LC3BI, LC3BII, MMP2, and MMP9 levels were significantly higher than in groups that did not receive PDT." (PMID 37239013, 2023).
squamous cell carcinoma (40 papers, 2002 to 2025). A carcinoma arising from squamous epithelial cells. "Using this method, cell death has been successfully induced in epidermolysis bullosa-associated squamous cell carcinoma cells, where the streptolysin O coding sequence was introduced at the 3′ of the matrix metalloproteinase-9 (MMP9) pre-mRNA." (PMID 35269953, 2022). "This function of MMP-9 as a regulator of paracrine interactions is supported by studies with MMP-9 deficient mice, which had delayed neoplastic progression and reduced proliferation in a model of squamous cell carcinoma." (PMID 27888810, 2016). "A previous study reported that MMP9 was correlated with invasion and metastasis of squamous cell carcinoma of the uterine cervix." (PMID 41312374, 2025). "There were no statistically significant changes observed in the frequency of the MMP-2-735C/T and MMP-9-1562C/T genotypes between patients with adenocarcinoma, squamous cell carcinoma, and other lung neoplasms." (PMID 37445754, 2023). "In the cell line of human squamous carcinoma, vitamin D3 was found to reduce the production of both MMP-9 and MMP-13 mRNA and proteins in a manner that is dependent on the dosage applied." (PMID 37299440, 2023). "In this context, one of our study’s aim was to observe the effects of lutein (100 mg) and lutein Nps on MMP-9 levels in human cells BICR10 (ECACC 04072103) of buccal mucosa squamous carcinoma." (PMID 34072756, 2021). "In the case of high expression of MMP-2 and MMP-9, both in tumor and its stroma, lower survival rates were demonstrated for squamous cell carcinomas of the tongue and digestive tract." (PMID 31223594, 2019). "This is in line with observation of Zuo et al49 who showed that pharmacologic inhibition of EGFR activity reduced the production of MMP‐9, as well as squamous carcinoma cell migration and invasion." (PMID 31638339, 2019). "Studies from the squamous carcinoma mouse model indicate that mast cells‐derived matrix metalloprotease 9 (MMP9) is important for the production of mature VEGF in the tumor microenvironment." (PMID 26992445, 2016). "Elevated serum MMP-9 correlated with distant metastasis and poor survival in patients with squamous cell carcinoma (SCC) over either the head and neck or the esophagus." (PMID 24476461, 2014). "Others have provided additional confirmation for Snail in inducing MMP-1, -2, -7 and -14 in liver and squamous cell carcinoma lines as well as MMP-9 in MDCK epithelial cells." (PMID 26932374, 2014). "MMP9 expression is regulated by NFκB, and in one study was shown to be correlated with NFκB activation in patients with squamous cell carcinoma of the uterine cervix." (PMID 23634849, 2013). "The objective of this study was to explore the effects of HB-EGF on proliferation, invasion activity and MMP-9 levels of an oral squamous cell carcinoma cell line, HSC3, in vitro." (PMID 22209887, 2012). "For example, in the media of sparse astrocytoma cells, more collagenase activity was seen than in dense cultures, and in epidermoid carcinoma cells, MMP9 secretion was detected only in sparse cultures." (PMID 14710237, 2004). "Induction of MMP-9 promoter activity by oncogenic Ras in squamous carcinoma cells has been shown to be abrogated by blocking the ERK 1/2 pathway." (PMID 12177807, 2002). "Thus, histological distinction (squamous cell carcinoma vs. adenocarcinoma) seems to be necessary in the analysis of tumor MMP-9 expression." (PMID 25888323, 2015). "Among patients with NSCLC, tumor MMP-9 expression was associated with poor outcomes in those with adenocarcinoma, but not in those with squamous cell carcinoma." (PMID 25888323, 2015). "The level of MMP-9 expression showed a statistically significant correlation (P < 0.001) with the disease histopathologic grade, stage, metastatic potential, recurrence potential, and survival in patients with squamous cell carcinoma of the larynx." (PMID 24476461, 2014).
squamous cell carcinoma (continued). "Exosomes isolated from patients with EGFR mutation showed significant increased activity of pro-MMP-9 and MMP-9 compared to exosomes isolated from serum from wild-type adenocarcinoma (ADK WT), squamous cell carcinoma, or healthy donors." (PMID 35954442, 2022). "Results indicated that c-Myc, c-Jun, Bcl-2, hypoxia inducible factor-1α (HIF-1α), vascular endothelial growth factor (VEGF), matrix metalloproteinase-9 (MMP-9), ERK 1/2 and pERK1/2 were overexpressed in a cellular model of squamous cell carcinoma, Cal-27." (PMID 35890188, 2022). "In squamous cell carcinoma H1703 cells, at 24 h, MMP-2, MMP-9, TIMP-1, and TIMP-2 in the MG showed higher expression than in the CONT." (PMID 31601869, 2019). "Vascular endothelial growth factor (VEGF), matrix metallopeptidase-9 (MMP-9) and tissue inhibitor of metalloproteinase-2 (TIMP-2) are potential markers of oral and maxillofacial squamous cell carcinoma (SCC)." (PMID 24829764, 2014). "Elevated MMP-9 has been reported to be at the invasive front of squamous cell and verrucous carcinomas in the oral cavity, indicating that MMP-9 expression is a reliable marker for invasive squamous cell carcinoma grading." (PMID 35784290, 2022). "Moreover, in squamous carcinoma both the over expression of Bcl-2 or EGFR activation induced EMT, promoting cell migration and invasion via the ERK1/2 and PI3K-regulated MMP-9/E-cadherin signaling pathways." (PMID 25277187, 2014). "Also, immunostaining of MMP-9 in squamous cell carcinoma tumors showed that MMP-9 was found only in tumor infiltrating leukocytes and not in tumor cells." (PMID 26819959, 2015). "However, subgroup analyses of tumor histology suggested that tumor MMP-9 expression was associated with decreased DFS and OS in patients with adenocarcinoma but not in those with squamous cell carcinoma." (PMID 25888323, 2015). "During collective cellular migration, which is the predominant pattern adopted by squamous cell carcinoma, MMP1 interacts with integrin α2β1 at the leading edge, and degrades native matrix macromolecules into fragments that are subsequently processed by the gelatinases MMP2 and MMP9." (PMID 24063540, 2013).
brain edema (39 papers, 2010 to 2026). Increased intracellular or extracellular fluid in brain tissue. "Evidence suggests that serum MMP-9 levels exceeding 140 μg/L can predict an increased risk of cerebral edema and poor prognosis in AIS patients." (PMID 40786638, 2025). "Proteolytic enzymes MMP-9 are sharply elevated in the early posttraumatic period and are key mediators of trauma-associated brain edema." (PMID 36466093, 2022). "The pro-inflammatory cytokine, interleukin-1β (IL-1β) as well as the proteolytic enzymes, matrix metalloproteinase-9 (MMP-9) are key mediators of trauma-associated brain edema." (PMID 27152411, 2016). "Activated MMP-9 degrades the extracellular matrix and destroys BBB integrity, causing vasogenic brain edema." (PMID 35814200, 2022). "The activation of MMP9 can increase the permeability of blood-brain barrier and aggravate the occurrence of brain edema." (PMID 33505489, 2021). "We wanted to know if miR-7-5p is also associated with MMP-9, ZO-1, occludin, TNF-α, IL-6, NLR, and CRP and if it jointly affects brain edema." (PMID 33392188, 2020). "In the present study, we showed that both gene deletion and pharmacological inhibition of sEH attenuated brain edema, MMP-9 activity and the expression of cytokines and chemokines." (PMID 29262558, 2017). "To explore the possible mechanism by which baicalin reduces ICH-induced brain edema, we determined the effect of baicalin on the MMP-9 expression." (PMID 23974988, 2014). "The present study also demonstrated increased MMP-9 expression and evident cerebral edema following HIBD." (PMID 23935758, 2013). "Furthermore, it induces the overexpression of matrix metalloproteinase-9 (MMP-9), which degrades blood-brain barrier tight junction proteins, compromises barrier integrity, and exacerbates vascular leakage and cerebral edema." (PMID 40529433, 2025). "The research also confirmed that the high expression of MMP9 can aggravate the destruction of blood–brain barrier and promote the occurrence of brain edema, and the purpose of relieving brain edema can be achieved by knocking out MMP9 in mice or using MMPs inhibitors." (PMID 34313877, 2022). "In the central nervous system diseases such as inflammation, MMP9 could lead to cerebral hemorrhage and brain edema by breaking the blood–brain barrier, and had toxic and side effects on neurons in varying degrees." (PMID 34313877, 2022). "In brief, intracerebral hemorrhage can cause inflammatory reactions by activating PMNs, microglia, and other cells, which can upregulate the expression of TNF-α, MMP-9, and other inflammatory cytokines, thereby causing BBB destruction and cell swelling and aggravating cerebral edema." (PMID 32564011, 2020). "Taken together, these indicated that MMP-9 overexpression was mediated by the p38 MAPK/ NF-κB signaling pathway, and in turn resulted in disruption of BBB integrity, causing the formation of brain edema during the course of 1,2-DCE-induced brain edema in mice." (PMID 31461951, 2019). "Anthocyanin could also markedly ameliorate cerebral edema and reduce the concentration of Evans blue (EB) by inhibiting MMP-9." (PMID 30618576, 2018). "Our results confirm that inhibition of MMP-9 may be useful in preventing cerebral edema, due to hypoperfusion and RE injury." (PMID 27445688, 2016). "MMP9 is one of the most closely related members of MMPs family with cerebrovascular diseases, which can degrade the components of cerebrovascular basement membrane, increase the permeability of blood–brain barrier, and aggravate the occurrence of cerebral edema after being activated." (PMID 34313877, 2022). "Although we have found that NF-κB could be activated through p38 MAPK signaling pathway during the course of 1,2-DCE-induced brain edema in mice, it is still unknown whether activation of NF-κB could enhance MMP-9 expression and whether BBB integrity might be disrupted by excessive MMP-9." (PMID 31461951, 2019).